TRAJ2 (T cell receptor alpha joining 2 (non-functional))
Gene: T-cell receptor joining (J) gene on chromosome 14 (22,544,071 to 22,544,136, forward strand). Ensembl gene ENSG00000211887.
Diseases named in the same sentence as TRAJ2 in open-access papers:
TRAJ2 is named in the same sentence as 1 disease in open-access papers, as found by Europe PMC text mining. Sharing a sentence is not in itself a finding about the gene and the disease.
TRAJ2 shares sentences with these, for which no sentence is quoted: COVID-19 (1 paper).